RHOA (ras homolog family member A)
Diseases named in the same sentence as RHOA in open-access papers (continued):
Sharing a sentence is not in itself a finding about the gene and the disease.
liver cancer (13 papers, 2015 to 2025). An epithelial or non-epithelial malignant neoplasm that arises from the liver. "Both Rac1 and RhoA have been implicated in invasive behavior of various tumor types including breast, lung, colon, and liver cancer." (PMID 35241781, 2022). "To explore the association between RhoA mRNA expression and OS in liver cancer patients, we performed Kaplan-Meier survival analysis based on data from TCGA." (PMID 31339860, 2019). "GTPases like RhoA and Rac1 were shown to be activated in hepatocellular carcinoma cell lines, due to electromagnetic forces causing cytoskeletal reorganization, which is known to facilitate liver cancer progression." (PMID 40171226, 2025). "The association between RhoA expression and the clinical parameters of patients with liver cancer." (PMID 31339860, 2019). "Furthermore, RhoA protein expression may be a diagnostic biomarker in HCC because its high liver cancer specificity was demonstrated by analyzing IHC sections from tumor resection margin areas of 9 HCC patients from PUMCH." (PMID 31339860, 2019). "The essential position occupied by RhoA in the cancer cellular signaling pathway network has emphasized the importance of RhoA in cancer pathophysiology, and the intrinsic characteristics of RhoA make RhoA a great potential distinguished diagnostic and prognostic biomarker for liver cancer." (PMID 31339860, 2019). "We provided the preliminary data for the mechanistic approaches of Neferine and proposed RhoA/Rho as one of its anti-HepG2 cell migration invasion pathways for multi-target therapy of liver cancer." (PMID 37446748, 2023). "We discovered that neuropeptide FF receptor 2 (NPFFR2) is aberrantly expressed in liver cancer and promotes malignancy by enhancing the activity of RhoA/YAP, and inhibiting NPFFR2 dramatically reduced the malignant phenotypes." (PMID 36497331, 2022). "It is shown that that stretching liver cancer cells significantly increases the expression levels of RhoA and Rac1 in HCC and cholangiocarcinoma cell lines." (PMID 32731493, 2020). "In the quest of elucidating the role of mechanical stimulation in the mechanobiology of liver cancer cells, this paper evaluates the effect of stretching on the expression levels of RhoA and Rac1 in different types of liver cancers." (PMID 32731493, 2020). "In conclusion, we observed the overexpression of Rho protein markers (RhoA and Rac1) in different liver cancer cells when they were stretched for a prolonged period." (PMID 32731493, 2020). "Here, using bioinformatics data mining, we found that both the gene and protein levels of RhoA were differentially expressed between liver cancer tissues and adjacent normal tissues, which indicated the potential of RhoA as a diagnostic biomarker." (PMID 31339860, 2019). "This differential RHOA activity determines polarized NC morphology and motility, and is regulated by the asymmetrically localized RhoGAP Deleted in liver cancer (DLC1) in the cytoplasm at the cell front." (PMID 29084958, 2017). "Therefore, we conducted the anti-migration experiment on liver cancer cells targeting RhoA and explored its mechanism." (PMID 37446748, 2023). "The previous study of liver cancer showed that overexpression of the RhoA protein could facilitate the migration and invasion of liver cancer cells." (PMID 37446748, 2023). "Interestingly, regarding RhoA protein expression, liver cancer exhibited a high positive rate, which ranked second among the positive expression rates of 20 common cancer types." (PMID 31339860, 2019). "Comparing normal liver tissue samples (225 patients) and liver hepatocellular carcinoma (LIHC) samples (371 patients), the expression of the genes: RhoA, Rac1, LIMK1, LIMK2, ROCK1, ROCK2, MLCK2, and PAK4 is upregulated in liver cancer." (PMID 35241781, 2022).
liver cancer (continued). "We previously reported that the RhoA up-stream regulators, DLC1 and DLC2 (deleted in liver cancer 1 and 2), were frequently down-regulated in human HCC by genetic deletion and epigenetic silencing." (PMID 25909223, 2015). "Wu found through network pharmacological analysis that the YQJPJD formula mainly regulates potential therapeutic targets of liver cancer through key ingredients such as luteolin, quercetin and baicalin and exerts anti-liver cancer effects through core targets such as RAC1, MAPK3, and RHOA." (PMID 39806972, 2025). "MiR-31 is well known metastatic suppressor by direct targeting integrin family, RhoA and RDX in various cancers but unknown in liver cancer." (PMID 25797269, 2015).
triple-negative breast carcinoma (13 papers, 2018 to 2025). An invasive breast carcinoma which is negative for expression of estrogen receptor (ER), progesterone receptor (PR), and human epidermal growth factor receptor 2 (HER2). "The inhibition of invasion by statins in the aggressive MDA-MB-231 triple-negative breast cancer cells has been attributed to the suppression of the RhoA/ROCK/NF-kB signaling pathway." (PMID 41155890, 2025). "In the present study, we demonstrated that TAZ knockdown inhibited the migration of highly invasive triple-negative breast cancer cells (MDA-MB-231) by reducing the protein abundance of RhoA and Rho-dependent kinases, particularly LIMK1 and MLCK." (PMID 38774409, 2024). "Low dox concentrations have been implicated in favoring the metastatic process of triple-negative breast cancer cells through activation of TGF-β1 and upregulation of the RhoA/MLC or Twist1 pathway." (PMID 39056658, 2024). "RKIP positively regulates the expression levels of E-cad on cell–cell junctions through RhoA in epithelial like triple-negative breast cancer cells." (PMID 34465801, 2021). "In these data, the expression of RhoA was approximately equivalent in the two groups but RhoB was much lower in the triple negative breast cancers." (PMID 33162807, 2020). "As RhoA and RhoB seem to have antagonistic roles in triple negative breast cancer, we studied the cellular effects of specific inhibition of RhoA or RhoB by siRNA." (PMID 33162807, 2020). "Taken together, these data suggest a higher RhoA/RhoB expression ratio in triple negative breast cancer cells but the comparison of 2 luminal cell lines to 5 triple negative cell lines is not very statistically relevant." (PMID 33162807, 2020). "Using the 4T1 triple negative breast cancer mouse model, we observed an inverse correlation between RhoA expression and infiltration of α-SMA positive CAFs." (PMID 31705019, 2019). "It has been shown that actin SF plays an essential role in promoting migration and metastasis of triple negative breast cancer in which RhoA can be activated by the interaction between Rhophilin-associated tail protein 1 (ROPN-1) and rhophilin-1 to enhance actin SF formation." (PMID 33158289, 2020).
glaucoma (12 papers, 2013 to 2024). Increased pressure in the eyeball due to obstruction of the outflow of aqueous humor. "RhoA protein levels in glaucoma optic nerve head (ONH) were substantially higher in patients with glaucoma than those in normal controls." (PMID 38155465, 2023). "The RhoA/ROCK pathway plays a role in the pathophysiology of glaucoma-induced optic nerve damage." (PMID 38155465, 2023). "Thus, RhoA can be used as a new target for the development of glaucoma medications." (PMID 33297931, 2020). "This study shows that ANGPTL7 transcriptionally regulated by SP1 can modulate CLAN formation via the RhoA/ROCK pathway and provides novel insights into how the TM ultrastructure and functions may be altered in some types of glaucoma." (PMID 35136015, 2022). "The involvement of RhoA/ROCK signaling in the pathogenesis of glaucoma is well established and led to the discovery of FDA approved Rho kinase inhibitors (RKI) such as ripasudil and netarsudil for glaucoma therapy." (PMID 32576873, 2020). "Elevated levels of RhoA are reported in the ONH of human eyes with glaucoma, and Rho kinase (ROCK) inhibitors are increasingly recognised as a promising therapeutic strategy for the treatment of glaucoma, indicating shared pathology." (PMID 27544758, 2016).
ischemic stroke (12 papers, 2013 to 2026). A stroke disorder caused by obstruction of blood flow to the brain, due to thrombotic (local blood clot formation) or embolic (due to a blood clot or other material traveling from another site) event. "The search strategy employed a combination of keywords and phrases related to ischemic stroke, molecular mechanisms, pharmacological treatments, RhoA/ROCK, mTOR pathways, MSCs, EVs, and secretome." (PMID 38666949, 2024). "The RhoA/ROCK pathway emerges as a pivotal player in ischemic stroke, orchestrating diverse cellular responses that contribute to both injury and repair processes." (PMID 38666949, 2024). "RhoA/Rock2 upregulation contributes to neuroinflammation, blood-brain barrier dysfunction, axon growth inhibition and neuronal apoptosis following ischemic stroke." (PMID 37789455, 2023). "Therefore, blocking the complete Nogo-A/RhoA/ROCK pathway is necessary to remove large obstacles that impede the neural regeneration process after ischemic stroke." (PMID 36142283, 2022). "In a recent study on the efficacy and mechanism of the traditional Chinese medicine naoluoxintong (NLXT) in ischemic stroke, expression of the Nogo-A/RhoA/ROCK genes, which was significantly upregulated in the ischemic stroke model, was found to be significantly reduced by NLXT treatment." (PMID 36142283, 2022). "Moreover, a sequential transcriptome analysis of the penumbra after ischemic stroke identified RHOA expression downregulation in the ipsilateral motor cortex, further supporting the viewpoint that RHOA could act as a biomarker for the penumbra." (PMID 36831829, 2023). "In conclusion, our review underscores the critical roles of the RhoA/ROCK and mTOR signaling pathways in ischemic stroke pathophysiology, alongside the emerging potential of secretome-based therapies." (PMID 38666949, 2024). "The RhoA-ROCK pathway participates in astrocyte-mediated angiogenesis and neurogenesis; inhibition of the RhoA-ROCK pathway can alleviate neuroinflammation, apoptosis, and oxidative stress, which are beneficial to neural recovery after an ischemic stroke." (PMID 37259366, 2023). "Our findings were consistent with previous reports showing upregulated NogoA/NgR and RhoA/ROCK-2, following ischemic stroke." (PMID 35559236, 2022). "In addition, inhibiting the RhoA/ROCK pathway may have deleterious effects on neuroinflammation, BBB dysfunction, neuronal apoptosis, astrogliosis, and axonal injury after ischemic stroke." (PMID 39766438, 2024). "Moreover, CDC42 and RHOA serve as key modulators in the cascade of ischemic stroke involving apoptosis, excitotoxicity, platelet function, neuroinflammation, and blood–brain barrier (BBB) balance, emphasizing CDC42 and RHOA as key endogenous mediators in the penumbra." (PMID 36831829, 2023).
Myocardial fibrosis (12 papers, 2016 to 2024). "MT improved cardiac function and myocardial fibrosis in rats by inhibiting the expression of the RhoA/ROCK1 signaling pathway." (PMID 39041001, 2024). "Uncaria rhynchophylla (UR) is known to have significant hypotensive effects and can attenuate Ang II-induced myocardial fibrosis by inhibiting the RhoA/ROCK1 signaling pathway." (PMID 36387359, 2022). "Our findings also demonstrate how nicorandil attenuates myocardial fibrosis through the down‐regulation of RhoA by targetting M2 macrophages." (PMID 29119680, 2018). "Matrine could inhibit the activation of RhoA/Rock1 signaling pathway, reduce myocardial fibrosis, prevent ventricular remodeling, and improve cardiac function in rats with heart failure." (PMID 35433636, 2022). "The RhoA/ROCK-1 pathway plays a significant role in myocardial fibrosis." (PMID 27611832, 2016). "The expression of RhoA and ROCK in several myocardial fibrosis models has been shown in earlier investigations." (PMID 38800023, 2024). "With these findings, we concluded that MFA suppressed proliferation and migration ability of HCFs and hence attenuated myocardial fibrosis, the mechanism of that was by suppressing the RB-E2F1/CCNE2 and the RhoA/ROCK2 pathway." (PMID 34483923, 2021). "Following these findings, we assumed that MFA attenuated proliferation and migration ability of HCFs and thus attenuated myocardial fibrosis by suppressing the pRB-E2F1/CCNE2 and the RhoA/ROCK2 pathway." (PMID 34483923, 2021). "The effects of QSKL on the MAPK and RhoA pathways were studied in order to reveal the antifibrotic mechanisms of QSKL and offer an alternative approach for the clinical treatment of myocardial fibrosis." (PMID 28484504, 2017). "RhoA, a small Rho family GTPase and an activator of serum response factor (SRF) signaling has also been shown to play an essential role in the control of myocardial fibrosis by regulating cofilins." (PMID 28886070, 2017). "Recent studies have determined that non-Smad pathways such as the RhoA/ROCK signaling pathway are also involved in myocardial fibrosis." (PMID 27611832, 2016).
viral infection (12 papers, 2011 to 2025). "Several studies have reported that viral infections are closely associated with the activation of the RhoA/ROCK1 signaling pathway." (PMID 40142587, 2025). "Recent studies have implicated the RhoA pathway in the pathogenesis of several viral infections, including Japanese Encephalitis virus (JEV), Ebola virus (EBOV), and Severe Acute Respiratory Syndrome Coronavirus 2 (SARS-CoV-2)." (PMID 40821819, 2025). "Virus infection causes modulation of MT dynamics by post-translationally modifying MTs through a RhoA-dependent mechanism." (PMID 32408515, 2020). "Most notably, we observed that inhibitors of the Rho GTPase family of cytoskeletal regulators—including RhoA, Cdc42, and Rho-associated kinase signaling pathways—significantly reduced viral infection." (PMID 28114951, 2017). "Furthermore, inhibition of cdc42, RhoA or Rho-associated protein kinase (ROCK) inhibited viral infection, demonstrating that the appropriate function of Rho family GTPases and their substrates is essential to optimal infection of CD4+ T cells." (PMID 29970186, 2018). "Next, we employed two chemical inhibitors, CCG-1423 and Y27632, to further investigate the impact of the RhoA/ROCK1/MLC2 signaling pathway on viral infection." (PMID 40142587, 2025). "It has been reported that RhoA and its downstream effectors were activated during certain virus infection." (PMID 37968757, 2023). "Human cytomegalovirus and herpes simplex virus type-1 have been shown to exploit RhoA and RhoB isoforms or other Rho family members, facilitating crucial steps of viral infection." (PMID 37968757, 2023). "The use of a RhoA, B and C inhibitor, as well as a Rac1 inhibitor, reduced virus infection." (PMID 40167026, 2025). "Interestingly, the evidence indicates that modulating RhoA activity by melatonin can improve host cell resilience, enhancing immune responses against viral infections." (PMID 40821819, 2025). "RhoA is a key regulator of cytoskeleton system that may participate in virus infection." (PMID 37968757, 2023). "Despite these advances in our understanding of Rho GTPase regulation of cytoskeletal dynamics and viral infection, the precise molecular mechanisms through which RhoA, Cdc42, and ROCK promote viral infection remain unclear and are currently under investigation." (PMID 28114951, 2017). "Although MVC infection activates the RhoA/ROCK1/MLC2 signaling pathway and significant effects on viral infection, our study still has some limitations." (PMID 40142587, 2025). "During the early stage of viral infection, MVC activates the RhoA/ROCK1/MLC2 signaling pathway." (PMID 40142587, 2025).
amyotrophic lateral sclerosis (11 papers, 2011 to 2026). Amyotrophic lateral sclerosis (ALS) is a neurodegenerative disease characterized by progressive muscular paralysis reflecting degeneration of motor neurons in the primary motor cortex, corticospinal tracts, brainstem and spinal cord. "Rho guanine nucleotide exchange factor (Rgnef/p190RhoGEF), a RhoA-specific guanine nucleotide exchange factor, has been implicated in cancer and amyotrophic lateral sclerosis, but little is known about its role in bone." (PMID 41571890, 2026). "Further, involvement of RhoA/ROCK signaling has been suggested in other neurodegenerative diseases, such as Parkinson's disease, Huntington's disease, and amyotrophic lateral sclerosis (ALS)." (PMID 25374504, 2014).